IL18 (interleukin 18)
Diseases named in the same sentence as IL18 in open-access papers (continued):
Sharing a sentence is not in itself a finding about the gene and the disease.
myocardial infarction (61 papers, 2009 to 2026). Gross necrosis of the myocardium, as a result of interruption of the blood supply to the area, as in coronary thrombosis. "IL-1β—and to a lesser extent IL-18—was elevated in adult cardiac cases, suggesting partial necroptosis activation during sterile cardiac stress, as has been previously implicated in myocardial infarction and ischemia–reperfusion injury." (PMID 40722817, 2025). "An increased concentration of IL-18 in the peripheral circulation has been associated with higher risk and incidence of ischemic events, including myocardial infarction." (PMID 40564918, 2025). "IL‐18 is associated with the development of cardiac conditions, such as heart attack and cardiac insufficiency." (PMID 39188114, 2024). "IL-18-rs187238 was significantly associated with decreased risks of myocardial infarction (MI) (allelic OR = 0.81, homozygous OR = 0.55, dominant OR = 0.80) and multiple vessel stenosis (allelic OR = 0.54, heterozygous OR = 0.45, dominant OR = 0.45)." (PMID 39766338, 2024). "We also found that the IL-18 polymorphisms were correlated with myocardial infarction (MI) and multivessel (MV) disease." (PMID 31661113, 2019). "Other members of the IL-1 family (such as IL-18 and IL-33) are also implicated in regulation of the inflammatory and reparative response following myocardial infarction." (PMID 26273700, 2015). "The increased levels of inflammatory cytokines, in particular, IL18, that occur as a response to viral influenza may increase the risk myocardial infarction." (PMID 31766396, 2019). "Furthermore, elevated levels of plasma IL-18 are observed in patients with previous myocardial infarction and are associated with the extent of coronary atherosclerosis." (PMID 21042583, 2010). "Caspase-1 deficient mice with myocardial infarction have displayed a significant reduction in mortality and reduced cardiomyocyte pro-apoptosis, decreased MMP-3 activity, and IL-18 production." (PMID 41231039, 2025). "Elevated IL-18 levels are associated with a higher risk of adverse clinical events after ACS, including recurrent unstable angina, myocardial infarction, heart failure exacerbation, stroke, and cardiovascular death." (PMID 41511355, 2025). "Studies have found that mice with myocardial infarction experience a decrease in left ventricular ejection fraction and increased expression of IL-1β, IL-18, and IL-10-mRNA after sleep deprivation." (PMID 40644492, 2025). "In a mouse model, modulation of IL-18 activity by administration of anti-IL-18 antibodies or mesenchymal stem cells overexpressing IL-18 binding protein has been shown to reduce myocardial infarct size." (PMID 40564918, 2025). "Colchicine blocks the assembly of the NLRP3 inflammasome, thereby reducing its activation and the release of proinflammatory cytokines such as interleukin-1β (IL-1β) and IL-18, key molecules in amplifying the inflammatory response after myocardial infarction." (PMID 41511355, 2025). "We found the elevation of IL-18, a cytokine, is involved in animal models of myocardial infarction with pressure overload effects." (PMID 37661270, 2023). "Previous studies also reported an increased expression of IL-18 in circulating T cells of patients with ischemic and dilated cardiomyopathy, and upregulation of IL-18 mRNA after myocardial infarction in mice." (PMID 36720768, 2023). "Activation of both NLRP3 inflammasome and caspase-11 inflammasome lead to the secretion of potent proinflammatory cytokines, IL-1beta and IL-18, which are well recognized as potential therapeutic targets for acute myocardial infarction." (PMID 37108494, 2023). "NLRP3, IL-1β, IL-18, and hsCRP levels were significantly higher in myocardial infarction patients compared to the healthy group (p = 0.02, p < 0.001, p < 0.001, and p < 0.001, respectively)." (PMID 37763063, 2023).
myocardial infarction (continued). "Circ-NNT or USP46 knockdown or miR-33a-5p overexpression inhibited the expression of pro-caspase-1, cleaved caspase-1, pro-caspase-11, cleaved caspase-11, IL-1β, and IL-18 in A/R cardiomyocytes and attenuated myocardial infarction in I/R mice." (PMID 34845193, 2021). "IL‐18 mediates cardiac dysfunction in animal models of acute myocardial infarction and pressure overload, and its inhibition protects against LPS‐induced myocardial dysfunction." (PMID 34472725, 2021). "Il-1 β and IL-18 inhibition have been shown to be effective in reducing major cardiac adverse events in clinical trials, including myocardial infarction and heart failure." (PMID 35069552, 2021). "In patients with acute myocardial infarction, omentin-1 negatively correlated with IL-18, and IL-18 remained an independent determinant of omentin-1 levels." (PMID 32375790, 2020). "Lipid concentrations, blood glucose, C-reactive protein (CRP), interleukin 18 and adiponectin are also commonly used as markers for heart attacks and have been shown to be increased in the obese." (PMID 32471361, 2020). "In people with stable and unstable angina and those with a recent myocardial infarction (MI), IL-18 was significantly higher than the control group." (PMID 31516856, 2019). "IL-18 neutralizing antibodies have been found to reduce the size of myocardial infarction in animal studies." (PMID 30366444, 2018). "Based on the inflammatory and fibrotic markers commonly observed in response to myocardial infarction and development of heart failure, we assessed the expression of mRNA for Tnfa, Il1b,Il6, Il18, Ccl2, Ccl3, Cxcl1, Cxcl2, Col1a1, Col3a1, Postn, and Tlr4 at 1 and 3 months." (PMID 35411847, 2022). "IL18 seems to be important indicator and predictor of cardiovascular death in two-year follow-up among non-diabetic patients suffering from chronic kidney disease, with a history of acute myocardial infarction in the previous year." (PMID 32297262, 2020). "Many molecules like troponins, brain natriuretic protein (BNP), ST2/IL-33, C-reactive protein (CRP), TNF, IL-1β, and IL-18 cytokines have been already examined as molecular markers for diagnosing or predicting different cardiac disturbances like myocardial infarction, heart failure, or myocarditis." (PMID 33172097, 2020). "Interleukin-18 (IL-18) is a potent pro-hypertrophic inflammatory cytokine and plays a critical role in the pathophysiology of various diseases including myocardial ischemia and myocardial infarction." (PMID 27888626, 2016). "Elevated levels of IL-18 mRNA have been measured in the myocardium of mice after the induction of myocardial infarction, while both increased and decreased IL-18 mRNA expression have been reported in myocardial tissue from human patients with ischemic and dilated cardiomyopathy." (PMID 21203448, 2010). "In a mouse model of myocardial infarction, small interfering RNA silencing of Clec7a downregulates the expression of NLRP3, IL-1β, and IL-18, thereby attenuating myocardial injury." (PMID 40243488, 2025). "The interaction effect between the IL-18 and average BDNF methylation levels on composite MACEs (p = 0.019) and myocardial infarction (p = 0.027) was significant after adjusting for covariates." (PMID 36499595, 2022). "The aim of this study was to check if serum interleukin-18 (IL-18) predicts 2-year cardiovascular mortality in patients at various stages of chronic kidney disease (CKD) and history of acute myocardial infarction (AMI) within the previous year." (PMID 26669254, 2015). "Importantly, KLX can ameliorate myocardial infarction-induced cardiac damage by inhibiting the expression of the NLRP3 inflammasome, reducing the release of proinflammatory cytokines IL-1β and IL-18, and suppressing pyroptotic cell death." (PMID 40148674, 2025).
myocardial infarction (continued). "The myocardial infarction area was significantly reduced in rats with myocardial infarction injected with KLF3-AS1 exosome, and the expressions of NLRP3, caspase-1, GSDMD, IL-1β and IL-18 in KLF3-AS1-overexpressed myocardial infarction mice were also significantly decreased." (PMID 37396588, 2023). "The higher circulating levels of IL-18 observed in patients with a previous myocardial infarction, is consistent with the literature, although not accompanied by higher expression of the corresponding gene in any adipose tissue compartment." (PMID 36644557, 2022). "For example, a 1-SD higher baseline serum level for each of IL-6, IL-18, and TNF-α is associated with a 10–25% higher risk of non-fatal myocardial infarction (MI) or coronary heart disease (CHD) death." (PMID 35997393, 2022). "Some inflammatory cytokines, including IL-1, IL-4, IL-6, IL-8, IL-18, and TGF-β1, are involved in the development of ischemic heart disease, myocardial infarction, and heart failure, thus, serving as potential targets for the development of some anti-ischemic therapies." (PMID 32104703, 2020). "BYHWD down-regulated IL-18, NLRP3 inflammatory vesicles, and TLR4/NF-κB signaling pathway by inhibiting the TLR4 signaling pathway, and suppressed the expression level of collagen I/III, thereby attenuating cardiac inflammation and myocardial fibrosis after myocardial infarction." (PMID 40881586, 2025). "Moreover, a meta-analysis of up to 29 population-based prospective studies, IL-6, IL-18, and TNF-α were all found to result in significantly higher relative risks for non-fatal myocardial infarction or CHD death after adjusting for traditional risk factors." (PMID 29750272, 2018).
colorectal cancer (55 papers, 2013 to 2025). A primary or metastatic malignant neoplasm that affects the colon or rectum. "Studies have demonstrated that the IL-18 gene -137G/C polymorphism is strongly associated with colorectal cancer, esophageal cancer, and other diseases." (PMID 40115022, 2025). "IL-18 secretion by the NLRP3 inflammasome can indirectly reduce tumor progression in colitis-associated colorectal cancer by inducing regulatory T (Treg) cells to produce IFN-γ and enhancing T-cell and NK-cell cytotoxicity." (PMID 39456655, 2024). "It has been shown that activation of inflammasome and IL-18 signaling pathway has a strong protective effect in colitis-associated colorectal cancer, among which NOD-like receptor protein 3 (NLRP3) is one of the most studied inflammasome." (PMID 39325798, 2024). "A case study reported that the BNT162b2 mRNA vaccine caused cytokine release syndrome including IL-18 level elevation in a colorectal cancer patient." (PMID 35251049, 2022). "Furthermore, IL-18 secretion mediated by the NLRP3 inflammasome can indirectly inhibit the tumor progression of colitis-associated colorectal cancer by inducing regulatory T (Treg) cells to produce IFN-γ and enhancing the cytotoxicity of T cells and NK cells." (PMID 37497237, 2023). "The IL18 promoter polymorphism –137G/C has previously been linked to various cancers in different populations, including esophageal squamous cell malignant tumors, prostate cancer in the Chinese population, colorectal cancer in Greek people, and ovarian cancer in native Hawaiians." (PMID 35794698, 2022). "In this regard, the ability of NLRP3 to protect against the development of colorectal cancer is attributed to the effector function of caspase-1 to mediate the secretion of IL-18." (PMID 40227443, 2025). "Other evidence for instance activation of NLRP3 in kupffer cells inhibited colorectal cancer liver metastasis by releasing IL‐18 and promoting maturation of hepatic NK cells." (PMID 40671401, 2025). "In colitis-associated colorectal cancer, the NLRP3 inflammasome acts as a negative modulator of tumorigenesis, because NLRP3-dependent IL-18 production promotes epithelial barrier healing, thereby preventing colorectal cancer progression and metastasis." (PMID 35740272, 2022). "In a recent study, a mix of lactobacilli strains were shown to increase the level of interleukin 18 in colorectal cancer (CRC) cells, which is recognized as an important cytokine for homeostasis of the gut epithelial cells and prevention of CRC progression." (PMID 35694291, 2022). "In the Hong clinical cohort, the expression of IL-18 was decreased in early-onset colorectal cancer samples compared with healthy control samples (P = 0.001)." (PMID 33294056, 2020). "A recent study demonstrated that T. musculis, a murine trichomonadid, can exacerbate colorectal cancer development through induction of IL-18 in mice." (PMID 31462294, 2019). "Exogenous IL-18 prevented these mutant mice from colorectal cancer and restored the migration of anti-tumorigenic T cells." (PMID 30717382, 2019). "IL-18 plays a critical role in mediating protection against colorectal cancer pathogenesis." (PMID 38886341, 2024). "In addition, NLRP3 was found to suppress hepatic metastasis of colorectal carcinoma by increasing the production of IL-18, thereby promoting NK cell maturation and cytotoxicity." (PMID 37289257, 2023). "IL-18, for its part, promotes the antitumor ability of NK cells in colorectal cancer." (PMID 36296636, 2022). "In contrast, caspase-1-activated IL-18 protects from colorectal cancer." (PMID 36581625, 2022). "During the early stage of colorectal cancer, elevated IL-18 secretion facilitated by NLRP1/NLRP3/pyrin could protect against colorectal cancer through the promotion of epithelial barrier regeneration during the early stages of colorectal cancer." (PMID 35990696, 2022).
colorectal cancer (continued). "Therefore, IL-18 signaling downstream of the NLRP3 inflammasome plays a central role in the protection against colorectal cancer progression." (PMID 34571825, 2021). "Moreover, ASC and caspase-1, as components of the inflammasome, and the downstream substrates of caspase-1; IL-1β and IL-18 were decreased in colorectal cancer cells." (PMID 34571825, 2021). "Hence, the protein downregulation of NLRP6, caspase-1 or IL-18 in epithelial tumor cells was correlated with a poor clinical outcome for colorectal cancer patients." (PMID 33255437, 2020). "NK cells exhibit an anti-tumour responses, therefore an increase in IL-18 secretion may be relevant to the anti-tumour activity of specific lactobacilli strains in rat colorectal cancer models." (PMID 32168834, 2020). "Indeed, in a mouse model of liver metastasis from colorectal cancers, NLRP3-/- mice showed reduced IL-18 expression and this was associated with increased liver metastasis." (PMID 33255437, 2020). "Therefore, IL‐18 signaling downstream of the NLRP3 inflammasome may be critical in preventing colorectal cancer development." (PMID 40671401, 2025). "NCF4 deficiency causes severe colorectal cancer in mice, increases transit-amplifying and precancerous cells, reduces the frequency and activation of CD8+ T and NK cells, and impairs the inflammasome-IL-18-IFN-γ axis during the early phase of colorectal tumorigenesis." (PMID 38886341, 2024). "In addition, IL-18 is also closely related to the development of colorectal cancer." (PMID 33776057, 2021). "Finally, the activation of NLRP3 inflammasome, with consequent production of IL-1β, IL-18 and procaspase-1 activation which induces pyroptosis (i.e. a form of programmed cell death), showed an anti-tumoral effect preventing/inhibiting colorectal cancer development." (PMID 32107391, 2020). "STING signaling is known to promote the production of interleukin-18 and IL-1β by macrophages through activation of NLRP3, mediating the anti-tumor function of NK cells to eliminate colorectal cancer liver metastases." (PMID 39325798, 2024). "In inflammatory bowel disease and colorectal cancer, the NLRP1 inflammasome exerts effects through IL-1β and IL-18." (PMID 37497237, 2023). "Patients with stomach and colorectal cancers have been reported to have CRS evidenced by raised inflammatory markers, thrombocytopenia, elevated cytokine levels (IFN-γ/IL-2R/IL-18/IL-16/IL-10), and steroid responsiveness." (PMID 35891179, 2022). "Intriguingly, IL18 and IL18RB expressions were significantly lower in colorectal cancer patients than colon biopsies from healthy donors." (PMID 30717382, 2019). "In addition, the inflammation molecules (IL-17, IL-2, IL-18, and IL-13) and oxidative stress capacity (GPx and SOD) were dysregulated in colorectal cancer as well as administration of 5-FU." (PMID 38637796, 2024). "Therefore, the hTERT promoter was used to drive the expression of IL-18 and HSV-TK in murine colorectal cancer cells as a novel cancer vaccine." (PMID 29703163, 2018). "One colorectal cancer patient with long-term anti-PD-1 monotherapy developed cytokine release syndrome (CRS) 5 days after receiving the Pfizer-BioNTech mRNA COVID-19 vaccine with evidence of increased inflammatory markers and elevated cytokine levels (IFN-γ, IL-2R, IL-18, IL-16, and IL-10)." (PMID 36033814, 2022). "IL-18 and HSV-TK combination gene therapy with the hTERT promoter may provide a new strategy of cancer gene therapy for the adjuvant therapy after curative resection of primary colorectal cancer." (PMID 25051201, 2014).